ENSG00000267618 (RAD51L3-RFFL readthrough)
Gene: Protein-coding gene on chromosome 17 (35,011,349 to 35,121,493, reverse strand). Ensembl gene ENSG00000267618.
Genetic constraint (gnomAD): Loss-of-function variants: 25 observed, 35.08 expected, observed/expected ratio (o/e) 0.71, 90% interval 0.52 to 1. Missense variants: 297 observed, 368.1 expected, observed/expected ratio (o/e) 0.81, 90% interval 0.73 to 0.89. Synonymous variants: 114 observed, 141.92 expected, observed/expected ratio (o/e) 0.8, 90% interval 0.69 to 0.94.